CD1A (CD1a molecule)
Diseases named in the same sentence as CD1A in open-access papers (continued):
Sharing a sentence is not in itself a finding about the gene and the disease.
invasive carcinoma (1 paper, 2021). A carcinoma that is not confined to the epithelium, and has spread to the surrounding stroma. "In respect of tumour histological type, a higher count of CD1a+ and CD123+ DCs was observed in invasive carcinoma of no special type compared to invasive lobular carcinoma." (PMID 33919875, 2021).
IPEX syndrome (1 paper, 2012). "A thymic biopsy showed absent CD1a and increased Bcl-2 (an anti-apoptotic protein) expression, due to a four point mutation in FOXP3 leading to translational frameshift, which is similar to IPEX syndrome." (PMID 22816667, 2012).
lymphoid neoplasm (1 paper, 2015). A neoplasm composed of a lymphocytic cell population which is usually malignant (clonal) by molecular genetic and/or immunophenotypic analysis. "In the present study, the tumor cells were positive for CD3 and thus, according to the World Health Organization (WHO) classification of lymphoid neoplasms guidelines, the immunological subtype was diagnosed as T-IV (positive for surface CD3 and negative for CD1a, irrespective of other markers)." (PMID 25624896, 2015).
measles (1 paper, 2019). A highly contagious viral infection caused by the measles virus. "Human KEGG pathway data of CD1A suggested that associated proteins influenced pathways involved in T-cell receptor signaling and response to pathogens such as trypanosomiasis, measles, and HTLV-1." (PMID 31475119, 2019).
mesothelioma (1 paper, 2015). A usually malignant and aggressive neoplasm of the mesothelium which is often associated with exposure to asbestos. "The upregulation of CD86 and downregulation of CD1a expression suggests that mesothelioma tumor cells induce partial iMoDC maturation." (PMID 25886502, 2015). "As the proportion of JU77 mesothelioma cells increased, the percentage of CD11c+ iMoDCs expressing CD1a decreased." (PMID 25886502, 2015). "The in vitro studies showed that mesothelioma cells and/or their factors initiated an early, but incomplete, maturation of iMoDCs, as evidenced by increased CD86 and reduced CD1a expression." (PMID 25886502, 2015).
metastatic tumor (1 paper, 2024). "Of note, all high CD1a-DCs cases had LN metastasis and CD1a-DCs were observed at the nearby metastatic tumor." (PMID 39684473, 2024).
nasal polyps (1 paper, 2013). "In the present study, immunohistochemical and double immunostaining methods were used to detect the expression and distribution of S-100 and CD1a/CD40 in the nasal polyps, to gain information concerning the role of DCs in their pathogenesis." (PMID 23737902, 2013). "As was observed for S-100, the CD1a and CD40 double stained-positive cells were mostly in the submucosa of the nasal polyps." (PMID 23737902, 2013).
nasopharyngeal carcinoma (1 paper, 2024). A carcinoma arising from the nasopharyngeal epithelium. "All subtypes of nasopharyngeal carcinoma presented with an inflammatory infiltrate with numerous plasma cells, eosinophils, and dendritic cells, presenting as antigen CD1a- and CD68-positive, as well as in CD117-positive mast cells." (PMID 38611634, 2024).
osteosarcoma (1 paper, 2016). A usually aggressive malignant bone-forming mesenchymal neoplasm, predominantly affecting adolescents and young adults. "Presence of a second APC, CD1a+ DCs, is also associated with poor survival in osteosarcoma." (PMID 27456063, 2016). "In conclusion, we have shown that tumor infiltration by either CD68+ TAMs or CD1a+ DCs may be associated with poorer survival in osteosarcoma." (PMID 27456063, 2016).
osteosclerosis (1 paper, 2018). Abnormally high bone density. "There are no diagnostic criteria for this entity, and diagnosis is usually based on radiologic findings of osteosclerosis combined with histopathological evidence of foamy CD68 positive and CD1a negative histiocytic infiltration." (PMID 29875943, 2018).
ovarian tumors (1 paper, 2009). "In this regard, it is noteworthy that ovarian tumors show low numbers of CD1a+ dendritic cells; perhaps CD20+ B cells serve as alternative antigen presenting cells in the tumor environment." (PMID 19641607, 2009).
Paget disease (1 paper, 2023). A malignant neoplasm composed of large cells with large nuclei, prominent nucleoli, and abundant pale cytoplasm (Paget cells). "Paget disease was associated with remarkably higher amounts of peritumoral CD1a+ DCs than in the case of its absence (pBH < 0.001)." (PMID 37373062, 2023). "If more than 100 CD1a+ DCs were counted, the odds of associated Paget disease were substantially higher (odds ratio: 13.22, 95% confidence interval: 2.99–58.39, pBH < 0.001)." (PMID 37373062, 2023). "The higher numbers of CD1a+ DCs are also associated with Paget disease." (PMID 37373062, 2023). "Furthermore, the number of DC-LAMP+ cells was higher in DCIS with comedo necrosis, ductal spread, lobular cancerization as well as comedo-type tumors, while CD1a+ cells were abundant in cases with Paget disease." (PMID 37373062, 2023).
periodontal disease (1 paper, 2009). "There was a significant increase in CD57+ cells and reduction in CD1a levels as periodontal disease progressed." (PMID 20379413, 2009). "The present study suggests that there was a decrease in CD1a expression in periodontal disease." (PMID 20379413, 2009). "The significant reduction in CD1a levels in periodontal disease when compared to health could possibly be a result of NK cells down regulating it." (PMID 20379413, 2009). "In the present study, we showed that there is an inverse relationship between CD1a+ LCs and CD57+ NK cells as periodontal disease progresses." (PMID 20379413, 2009).
phlebitis (1 paper, 2025). Inflammation of a vein. "The diagnosis is based on a combination of clinical features and histopathological findings, including the classification of lesions, the presence of polygonal histiocytes with emperipolesis, positive staining for S-100 and CD68 proteins, negative staining for CD1a, and the absence of phlebitis." (PMID 40895985, 2025).
plaque psoriasis (1 paper, 2023). "To detect the frequency of CD1a-LPC-reactive T cells in individuals with plaque psoriasis, we next tetramerized CD1a monomers treated with CHAPS detergent (mock) or different species of LPCs, and stained polyclonal blood T cells." (PMID 37267382, 2023). "Given we have demonstrated here that GAS can drive a CD1a-autoreactive effector T cell response, we next tested whether individuals with plaque psoriasis have altered frequency and phenotype of GAS-responsive T cells." (PMID 37267382, 2023).
Pleural effusion (1 paper, 2018). The presence of an excessive amount of fluid in the pleural cavity. "Remarkably, using concentrations of TGF-β similar to those found at inflammatory sites such as pleural effusions, synovial fluid, and tumor-derived ascites (~0.25 ng/ml), we found that all concentrations of PGE2 assessed markedly suppressed the expression of CD1a, preserving CD14 expression." (PMID 29988364, 2018).
primary sclerosing cholangitis (1 paper, 2015). "The presence of CD1a-positive cells aids in the distinction between primary sclerosing cholangitis, which may be difficult if the biopsy is done very late with only fibrotic lesions." (PMID 25977828, 2015).
pulmonary aspergillosis (1 paper, 2014). "In human neutropenic pulmonary aspergillosis there is significant pulmonary recruitment of CD1a+ DCs, which represent monocyte-derived cells." (PMID 24586155, 2014).
scrub typhus (1 paper, 2013). Scrub typhus is a rare dust mite-borne infectious disease caused by the Orientia tsutsugamushi bacterium and characterized clinically by an eruptive fever which is potentially serious. "Recently, a paper reported that O. tsutsugamushi mainly infects “inflammatory” CD14/LSP-1/CD68 positive monocytes and CD1a/DCSIGN/S100/FXIIIa and CD163 positive dendritic cells in stained eschar skin biopsies from scrub typhus patients." (PMID 23301113, 2013).
Splenomegaly (1 paper, 2022). Abnormal increased size of the spleen. "We confirmed CD1a-dependence showing that administration of anti-CD1a not only ameliorates cutaneous inflammation but also systemic inflammation as measured by splenomegaly, cellular infiltration and plasma cytokine secretion." (PMID 36477177, 2022).
ST Elevation Myocardial Infarction (1 paper, 2022). A myocardial infarction that produces elevation in the ST segments of the ECG. "They found a downregulation of immature (CD1a+) DCs in ST-elevation myocardial infarction (STEMI), non-STEMI, and coronary artery disease (CAD) patients and an upregulation of mature (CD86+) DCs in CAD patients." (PMID 35615580, 2022).
T-cell neoplasms (1 paper, 2022). "Similarly, there have been reports of mature T-cell neoplasms aberrantly expressing immature markers, such as CD1a." (PMID 35359424, 2022).
thyroid carcinomas (1 paper, 2014). "We investigated 65 patients with different types of thyroid carcinomas: papillary (PTC), oncocytic (OTC), follicular (FTC) and anaplastic (ATC), immunohistochemically with antibodies against VEGF, CD1a, CD83, S100 and CD31." (PMID 26019537, 2014).
trichoblastoma (1 paper, 2015). A benign hair follicle neoplasm with trichoblastic differentiation. "In contrast with adamantinoid trichoblastoma (that also shows cytoarchitecturalcompartmentalization of the cell aggregates in a peripheral germinative cell and acentral pale cell area), no lymphocytes or S100/CD1a-positive dendritic cells arefound in trichogerminoma." (PMID 26734858, 2015).
tuberculoid leprosy (1 paper, 2025). A principal or polar form of leprosy in which the skin lesions are few and are sharply demarcated. "There is also a significant reduction of CD1a+ cells in lesions compared to tuberculoid leprosy." (PMID 41328285, 2025).
undifferentiated nasopharyngeal carcinoma (1 paper, 2024). "The positive CD1a and CD68 antigen-presenting cells were observed in most cases of undifferentiated nasopharyngeal carcinoma (88%), being between 5 and 15% of the peri- and intratumor inflammatory infiltrate, with an intratumor predominance." (PMID 38611634, 2024).
uveal melanoma (1 paper, 2016). A melanoma derived from melanocytes of the uveal tract. "Uveal melanoma cell co-cultured DCs exhibited decreased expression of CD1a and CD83 and impaired T cell activation." (PMID 27556503, 2016).
tumor (156 papers, 1999 to 2026). "The factors significantly associated with DSS were the M stage (p = 0.010) and CD1a-DCs in tumor (p = 0.001)." (PMID 39684473, 2024). "Previous reports have indicated that infiltration of CD1a-DCs into the primary tumor is associated with favorable clinical outcomes in GBC." (PMID 39684473, 2024). "Previous reports have indicated that tumor infiltration by CD1a positive DCs (CD1a-DCs) was associated with favorable clinical outcomes in GBC." (PMID 39684473, 2024). "The factors significantly associated with RFS were the M stage (p = 0.017) and CD1a-DCs in tumor (p = 0.001)." (PMID 39684473, 2024). "Immunohistochemistry shows positivity for S100, CD1a, and Langerin in the tumor cells; genetic testing reveals BRAF gene mutations in more than 50% cases." (PMID 38706599, 2024). "The factors significantly associated with OS were M stage (p = 0.049), CD1a-DCs in tumor (p = 0.002) and adjuvant therapy (p = 0.010)." (PMID 39684473, 2024). "This pattern of expression makes the targeting of CD1a less prone to fratricide effects and potentially reduces the risk of on target/off-tumor side effects." (PMID 36624522, 2023). "Several reports have indicated that the infiltration of CD1a-positive (CD1a+) DCs into tumor tissue is associated with favorable clinical outcomes in carcinomas of the ovary, oral cavity, thyroid and gallbladder." (PMID 34461859, 2021). "AKT3 expression in CAFs was significantly positively correlated with the proportion of α-SMA-positive CAFs (p < 0.001), number of CD68+ tumor-associated macrophages (p = 0.01), number of CD1a+ dendritic cells (p = 0.02), and number of CD3+ T cells (p = 0.03)." (PMID 33799788, 2021). "Regression analysis using chi square test confirmed a highly significant correlation between loss of CD1A protein expression (< 1%) and occurrence of an early post-surgical relapse (p = 0.0226 for tumor cells and p = 0.0012 for immune cells)." (PMID 33953302, 2021). "Similar, but non-significant, trends towards an association with survival were seen in PB-type tumours when CD1a+ DC density in stroma or tumour-nest was analysed separately (data not shown)." (PMID 28673320, 2017). "In other human malignancies the decreased number of CD1a-positive DCs in tumor area is often associated with the progression of the disease and unfavourable prognosis." (PMID 28331853, 2017). "The presence of a consistent number of CD1a+ cells in the tumor microenvironment is associated with a better prognosis." (PMID 27088097, 2016). "Accompanying the tumor-associated shifts in the CD1a/CD14 frequencies, CD83 frequencies also shifted in concordance with a mature state of the CD1a+ DC and an immature state of the CD14+ DC." (PMID 23875023, 2013). "CD1a has been used as a marker for DCs in a range of human tumours and the density of CD1a DC has been associated with clinical outcome." (PMID 12888826, 2003). "The association between MHC and CD1a expression in tumours is currently unclear, but this study appears to exclude major down regulation of CD1a expression as an additional deficit." (PMID 11870535, 2002). "The presence of a high number of infiltrating CD1a+cells in malignant neoplasms has been reported to be associated with an improved prognosis, reduced tumour recurrence and fewer metastases." (PMID 10070894, 1999). "Furthermore, in HCC tumor infiltration high prevalence of IL-37+CD1a+ DCs biopsies was linked to higher survival rates of patients." (PMID 36551790, 2022). "Similarly, the most intense infiltration of intratumoural CD1a+ cells was associated with G3 tumours; however, it differed significantly only with G2 tumours (p < 0.015)." (PMID 33919875, 2021). "Lipid-laden iMoDCs demonstrated reduced CD1a expression, which may decrease presentation of tumor-associated lipid antigens and reduce activation of lipid-specific T cells." (PMID 25886502, 2015). "In cancer patients, reductions in tumor-infiltrating CD1a+ DCs are associated with poor prognosis." (PMID 25886502, 2015).
tumor (continued). "CD1A dysregulation could negatively impact activation of suppressor and regulatory T cells systemically as well as tumor associated macrophages in the microenvironment, benefiting patients with HPV+ cancers." (PMID 26518708, 2015). "The presence of high numbers of mature CD208+ infiltrating dendritic cells (DC) in the tumour epithelium has been associated with shorter overall patient survival, while patients with high numbers of CD1a+ DCs in the advancing margin of the tumour appear to have a shorter disease-free survival." (PMID 21339979, 2010). "Indeed, the density of CD1a+ DCs within human tumours has been already associated with longer survival." (PMID 15756258, 2005). "There was clear evidence, however, that the CD1a+cells were closely associated with tumour cells." (PMID 10070894, 1999). "Similarly, a decrease in CD1a+ cells in SLNs was associated with tumor involvement." (PMID 35955602, 2022). "It has been speculated that a higher density of CD1a+ DCs in tumor tissue correlates with favorable clinical outcomes, and several studies have reported that tumor-infiltrating CD1a+ DCs were associated with favorable clinical outcomes in carcinomas of various organs." (PMID 34461859, 2021). "However, testing a panel of tumor-associated culprits pointed to IL-10 as the most likely candidate, since it was the only tested cytokine that could affect the balance of migrating CD1a+ and CD14+ DDC." (PMID 23875023, 2013). "This study aimed to evaluate the expression of Wnt/β-catenin pathway components and tumor-associated markers-including COX-2, Ki-67, tryptase, CD1a, and WNT3A-across different histopathological subtypes of BCC." (PMID 42194765, 2026). "Similar mechanism can be responsible for higher densities of CD1a+ DCs in the tumor interior of LM vs tumor exterior." (PMID 41410751, 2025). "The diagnosis of LCH is established by identifying clonal tumor proliferation, characterized by the expression of CD1a, CD207 (Langerin), and S100 proteins." (PMID 41426579, 2025). "Their study demonstrated a strong correlation between reduced CD1a+ cell density in tumor‐adjacent tissues and adverse clinical outcomes, including DFS and OS." (PMID 39888250, 2025). "The second pathological examination revealed that the tumor cells expressed CD1a, S-100, and Langerin with BRAF (c.1457_1471del) deletion mutations." (PMID 39911823, 2024). "Our result that CD1a-DCs are significantly more induced in metastatic LNs than in non-metastatic LNs supports the theory that CD1a-DCs are developed at tumor sites." (PMID 39684473, 2024). "For several tumor entities, the density of CD1a+ DCs has been shown to correlate with improved clinical outcomes." (PMID 39768204, 2024). "By immunohistochemistry, tumor cells specifically express CD1a, langerin, and S-100; thus, the minimal panel of antibodies should include those against langerin and CD1a." (PMID 38652382, 2024). "Immunohistochemically, all the tumor cells were strongly positive for S-100, CD1a, and langerin, and the Ki-67 labeling index was 2% to 30%." (PMID 39705477, 2024). "Bell observed a higher CD83 concentration in the peri-tumoral area and a higher CD1a concentration within the tumor tissues." (PMID 39529763, 2024). "Mature DCs (CD83+) are primarily located at the invasive tumor margins in iCCA, while a considerable number of immature DCs (CD1a+) are found inside the tumor." (PMID 39456636, 2024). "The results of strong confounding between CD1a-DCs and LN metastasis support the theory that CD1a-DCs are developed from monocytes at tumor sites." (PMID 39684473, 2024). "The factors significantly associated with DSS were T stage (T1/T2 vs. T3/T4; p < 0.000), N stage (N0 vs. N1/N2; p = 0.000), M stage (M0 vs. M1; p = 0.000), CD1a status in tumor (high vs. low; p = 0.041) and CD1a-DCs status in LN (high vs. low; p = 0.010)." (PMID 39684473, 2024).